PRNP (prion protein (Kanno blood group))
Diseases named in the same sentence as PRNP in open-access papers (continued):
Sharing a sentence is not in itself a finding about the gene and the disease.
Gerstmann-Sträussler-Scheinker disease (22 papers, 2008 to 2025). "Whole-genome sequencing revealed a heterozygous pathogenic variant, c.305C > T; p.Pro102Leu, in the PRNP gene, which is consistent with Gerstmann-Sträussler-Scheinker disease." (PMID 41142443, 2025). "This study aimed to determine the pattern of [18F]flortaucipir uptake in individuals affected by Gerstmann-Sträussler-Scheinker disease (GSS) associated with the PRNP F198S mutation." (PMID 30373672, 2018). "Autosomal dominant inheritance of PRNP mutations may also lead to another form of human TSE named as Gerstmann-Sträussler-Scheinker Syndrome (GSS)." (PMID 22196171, 2011). "Similarly, in genetic prion diseases such as familial CJD (fCJD), fatal familial insomnia (FFI), and Gerstmann-Sträussler-Scheinker disease (GSS), mutations within the PRNP gene encoding PrP are believed to promote the spontaneous formation of PrPSc." (PMID 39087478, 2024). "It is well established that similar PrPSc fragments also characterize the so-called inherited prion protein amyloidoses, including Gerstmann-Sträussler-Scheinker disease (GSS), and the cerebral and systemic amyloidosis that are linked to stop-codon truncating PRNP mutations." (PMID 35215959, 2022). "However, some, and in particular an extensively studied type of Gerstmann-Sträussler-Scheinker syndrome (GSS) caused by a PRNP A117V mutation, are thought not to generate infectious prions and instead constitute prion proteinopathies with a quite distinct pathogenetic mechanism." (PMID 24086135, 2013). "A causal role for copy number variation (CNV) in the prion protein gene (PRNP) in prion dementias is not known." (PMID 21193246, 2012). "In contrast, BN seem to be rare in non-Japanese cases of PE-CJD but in a case of prion dementia without characteristic pathology, related to an insertional PRNP aberration, a few BN were already seen in the cortex." (PMID 22551916, 2012).
glioblastoma (22 papers, 2011 to 2025). The most malignant astrocytic tumor (WHO grade IV). "For instance, overexpression of PRNP was reported to be associated with increased stemness of tumor cells in glioblastoma, pancreatic ductal adenocarcinoma, and osteosarcoma." (PMID 36213323, 2022). "We suggested the possibility that somatic mutations of the PRNP gene in glioblastoma can be masked by a diagnosis of prion disease." (PMID 32560489, 2020). "TGF and associated metastatic processes are strongly linked to poor survival; thus, it is also critically noted that high PRNP levels also predict poor survival in Kaplan–Meier analyses of colon and liver carcinomas as well as glioblastoma." (PMID 40562790, 2025). "An over-expression of PRNP, unrelated to age, gender and stage, was initially reported in diverse types of solid cancers notably glioblastoma (GBM), pancreatic ductal adenocarcinoma (PDAC) and lung adenocarcinoma (LAC), CRC, GC and breast cancer (BC)." (PMID 37452879, 2023). "As PRNP is highly expressed in the CNS, we chose a glioblastoma cell line U251-MG for the initial round of screening, additionally due to the suitability of this cell line in high-throughput screenings." (PMID 34705895, 2021). "No somatic mutation of the PRNP gene has been found in breast cancer and glioblastoma, indicating that PRNP is a tumor suppressor gene." (PMID 36980514, 2023). "Strikingly, although invasive breast carcinoma and glioblastoma accounted for a high percentage of the total cancer patient population (9.9% and 5.4%, respectively), somatic mutations in the PRNP gene have not been identified in these two cancer types." (PMID 32560489, 2020). "Notably, although invasive breast carcinoma and glioblastoma account for a high percentage of the total cancer patient population (9.9% and 5.4%, respectively), somatic mutations in the PRNP gene have not been identified in these two cancer types." (PMID 32560489, 2020). "Notably, although invasive breast carcinoma (9.9%) and glioblastoma (5.4%) account for high percentage of the total cancer patient population, somatic mutation of the PRNP gene has not been identified in these two cancer types." (PMID 32560489, 2020).
Ataxia (19 papers, 2009 to 2025). Ataxia refers to impaired coordination of voluntary muscle movement. "The PRNP (F198S) mutation carriers present clinically with a GSS syndrome characterized by cerebellar ataxia, dysarthria, and progressive pyramidal and parkinsonian signs." (PMID 35819518, 2022). "The E146G PRNP mutation, identified for the first time in this family, was associated with a gradual neurodegenerative disease progressing over around 8 years with variable motor onset (prominent action myoclonus/dysarthria/ataxia) and later cognitive decline." (PMID 40156621, 2025). "Both cognitive decline and ataxia characterized the clinical onset in approximately half of the patients with 129M-type 1, without significant differences among PRNP mutations (online resource)." (PMID 34324063, 2021).
colon carcinoma (15 papers, 2015 to 2025). "PRNP expression is highly associated with the EMT signature in colon cancer patients, and PrPC is known to control the expression of ZEB1 in colon cancer cells." (PMID 33276687, 2020). "Elevated expression of PRNP in homozygous mice was accompanied by increased expression of a set of genes that we previously identified as PrPC gene targets in colon cancer cells, namely App, Bace1, Dkk3, Pdgfc and Tgfb1, thus validating our model as a robust PRNP-overexpressing paradigm." (PMID 38589873, 2024). "We found that the PRNP promoter is occupied by β-catenin and harbors the active H3K4me3 mark (H3 histone tri-methylated on Lysine 4) in SW480 and DLD1 colon cancer cells in the GSE156083 dataset." (PMID 38589873, 2024).
glioma (13 papers, 2013 to 2025). A benign or malignant brain and spinal cord tumor that arises from glial cells (astrocytes, oligodendrocytes, ependymal cells). "Among various tumor tissues, the PRNP mRNA expression is the highest in low-grade glioma, followed by squamous cell carcinoma of head and neck, while its expression is the lowest in hepatocellular carcinoma." (PMID 38370370, 2024). "Bioinformatics analysis using TIMER2.0 and GEPIA 2.0 revealed positive correlations between CLU expression and several genes (BAX, BCL2L1, PRNP, HSPA5, LRP2, TTR, all p < 0.05), suggesting synergistic or antagonistic interactions during glioma development." (PMID 40606578, 2025).
cognitive decline (12 papers, 2016 to 2025). "The proband’s cognitive decline and relatively slow disease progression in addition to his symptoms resemble the previously published cases with 168 bp insertion in the PRNP gene." (PMID 35752680, 2022). "The bioinformatics data together indicate that upregulation of SERPINA1, VCP, PRNP, CIP2A, HSPA9, and UQCRC2 and downregulation of IGFBP3, CRHBP, PEPD, and GUSB were correlated to cognitive decline in T2DM patients." (PMID 36506101, 2022). "By integrating proteomics and machine learning data, we identified that changes in PRNP, CRHBP, VCP, and rGSK-3β had the greatest power to identify cognitive decline in T2DM patients." (PMID 36506101, 2022). "Further machine learning data showed that increases in PRNP, CRHBP, VCP, and rGSK-3β(T/S9) (ratio of total to serine-9-phosphorylated glycogen synthase kinase-3β) had the greatest power to identify mild cognitive decline in T2DM patients." (PMID 36506101, 2022). "Among them, the increases in PRNP, CRHBP, VCP, and rGSK-3β(T/S9) had the greatest power to identify cognitive decline in T2DM patients." (PMID 36506101, 2022). "Further studies by ELISA and Peterson’s analyses validated that the upregulation of CIP2A, PRNP, and CRHBP and downregulation of VCP were indeed correlated to cognitive decline in T2DM patients." (PMID 36506101, 2022).
pancreatic cancer (11 papers, 2019 to 2025). "Previous studies have linked PRNP overexpression to the initiation and progression of multiple cancers, such as gastric, colorectal, lung, and breast cancers, as well as pancreatic cancer and gliomas." (PMID 41394830, 2025). "The research reveals a significant correlation between PRNP expression levels and gemcitabine resistance, providing a novel perspective for deciphering the mechanisms of chemotherapy resistance in pancreatic cancer." (PMID 41394830, 2025). "To investigate the synergistic apoptotic effect of gemcitabine and PRNP silencing in pancreatic cancer cells, we first used MTT assays and colony formation analysis to quantify cell viability and clonogenic survival." (PMID 41394830, 2025). "qRT–PCR and Western blot were employed to confirm that GEM enhances PRNP gene expression in pancreatic cancer cells (p < 0.05)." (PMID 41394830, 2025). "Cell colony formation and trypan blue staining experiments were conducted, and the silencing of PRNP enhanced the toxic effect of gemcitabine on pancreatic cancer cells." (PMID 41394830, 2025). "In the present study, we aimed to investigate the mechanism by which PRNP modulates the response of pancreatic cancer to gemcitabine treatment." (PMID 41394830, 2025). "For the first time, through integrated multi-cohort analysis and functional cell experiments, it confirms that PRNP serves as a potential molecular target for gemcitabine therapy in pancreatic cancer." (PMID 41394830, 2025). "This study systematically delineates the differential regulatory networks governing pancreatic cancer cell death modes induced by PRNP silencing, gemcitabine monotherapy, and their combination." (PMID 41394830, 2025). "Based on previous findings, we confirmed that gemcitabine-induced PRNP upregulation facilitates the generation of iCAFs in pancreatic cancer." (PMID 41394830, 2025). "To delve deeper into the expression patterns of PRNP in pancreatic cancer samples and the primary cell types that impact them, we conducted an analysis utilizing spatial transcriptomics technology." (PMID 41394830, 2025). "In summary, gemcitabine triggers EMT and ferroptosis resistance mechanisms in pancreatic cancer cells by upregulating PRNP expression." (PMID 41394830, 2025). "The results of the Transwell invasion assay aligned with those of the migration assay (p < 0.05), demonstrating that silencing PRNP enhances the inhibitory effect of gemcitabine on pancreatic cancer cell invasion." (PMID 41394830, 2025). "Integrating the results of PRNP silencing and pharmacological interventions, we conclude that PRNP exerts a critical ferroptosis-suppressing role in pancreatic cancer cells by positively regulating SLC7A11 and GPX4 protein expression." (PMID 41394830, 2025). "MTT analysis demonstrated that adding 1 μM Ferrostatin-1 to pancreatic cancer cells with silenced PRNP gene significantly suppressed the cell death process, initially suggesting an intrinsic link between Ferrostatin-1 and PRNP gene expression regulation." (PMID 41394830, 2025). "Bioinformatics analysis revealed that gemcitabine treatment of pancreatic cancer cells increases PRNP expression while inducing EMT." (PMID 41394830, 2025). "In pancreatic cancer specifically, elevated PRNP expression is recognized for its role in activating EMT-related pathways, thereby promoting tumor invasion and conferring resistance to chemotherapy." (PMID 41394830, 2025). "In summary, PRNP gene expression is elevated in CAF subpopulations of pancreatic cancer patients post-chemotherapy, fostering the emergence of EMT-related genes and drug resistance mechanisms." (PMID 41394830, 2025).
pancreatic cancer (continued). "Additionally, silencing PRNP concurrently decreases mitochondrial membrane potential in pancreatic cancer cells, leading to mitochondrial damage and stimulating autophagy." (PMID 41394830, 2025). "Taken together, the results of the wound-healing and Transwell assays indicate that GEM affects the EMT pathway to inhibit the migration and invasion abilities of pancreatic cancer cells and that silencing the PRNP gene synergistically inhibits the EMT process in pancreatic cancer cells with GEM." (PMID 41394830, 2025). "Importantly, the combination of gemcitabine and siPRNP produced a synergistic apoptotic response, indicating that PRNP silencing enhances gemcitabine-induced apoptosis in pancreatic cancer cells." (PMID 41394830, 2025). "Collectively, these findings imply that PRNP could serve as target for gene therapy in pancreatic cancer, offering new insights for the future clinical application of gemcitabine." (PMID 41394830, 2025). "To explore whether Ferrostatin-1 and PRNP in silenced pancreatic cancer cells are involved in the ferroptosis pathway, we assessed key ferroptosis related indicators." (PMID 41394830, 2025). "While the relationship between PrPC and the pathogenesis of prion disorders has been largely established, the link between PrPC and cancer progression was first reported when PrPC gene (PRNP) was identified as one of the most expressed in pancreatic cancer (PC) cells." (PMID 37452879, 2023). "Furthermore, the number of cells that passed through the chamber in the siPRNP+GEM group was even greater than that in the GEM group, suggesting that PRNP knockdown augments the inhibitory effect of gemcitabine on the migration of human pancreatic cancer cells (p < 0.05)." (PMID 41394830, 2025). "Notably, PRNP silenced pancreatic cancer cells exhibit significantly enhanced ferroptosis responses when exposed to gemcitabine, suggesting that PRNP dysfunction may sensitize pancreatic cancer cells to gemcitabine-induced ferroptosis." (PMID 41394830, 2025). "By silencing of PRNP abrogated GEM-induced EMT and conferred concomitant sensitization to ferroptosis, thereby promoting apoptosis in pancreatic cancer cells." (PMID 41394830, 2025). "To validate PRNP expression in chemotherapy-treated patients, we examined genes expression within the PRJNA694728 gemcitabine-resistant pancreatic cancer patient-derived xenograft (PDX) model transcriptome dataset." (PMID 41394830, 2025). "We observed that, upon silencing the PRNP gene, GEM significantly accelerated the reduction in the mitochondrial membrane potential in pancreatic cancer cells, suggesting that silencing PRNP facilitates ferroptosis induction." (PMID 41394830, 2025). "To explore the role of PRNP in ferroptosis, we employed the DCFH-DA ROS fluorescent probe to monitor ROS production in pancreatic cancer cells after GEM treatment." (PMID 41394830, 2025). "The relationship between PrPC and cancer progression was first discovered when PRNP was identified as one of the most-expressed genes in pancreatic cancer cells." (PMID 33276687, 2020). "Upon silencing the PRNP gene, GEM markedly augmented ROS generation in pancreatic cancer cells." (PMID 41394830, 2025). "Notably, PRNP showed the strongest positive correlation with RRM1 (Pearson’s R = 0.37, p < 0.05), supporting its prioritization as a potential therapeutic target for overcoming gemcitabine resistance in pancreatic cancer." (PMID 41394830, 2025).
melanoma (10 papers, 2020 to 2025). A malignant, usually aggressive tumor composed of atypical, neoplastic melanocytes. "In melanoma, PrPC also exists in the pro-PrPC form, and in FLNa deficient melanoma cell lines, modulations in the PRNP gene expression affect cell migration." (PMID 32932634, 2020).
kuru (9 papers, 2017 to 2025). A prion disease found exclusively among the Fore linguistic group natives of the highlands of new guinea. "Epidemiological evidence demonstrated that PRNP polymorphisms influence susceptibility to kuru, similar to the genetic control of scrapie incubation period in mice." (PMID 34064393, 2021).
tauopathy (8 papers, 2017 to 2025). Neurodegenerative disorders involving deposition of abnormal tau protein isoforms (tau proteins) in neurons and glial cells in the brain. "In some GSS familiar cases carrying point mutations in the PRNP gene, patients also showed comorbid tauopathy leading to mixed pathologies." (PMID 28466265, 2018). "Factors such as codon 129 polymorphism in PRNP, the presence of PrPSc isoforms, and co-pathologies (e.g., tauopathy) may explain this heterogeneity." (PMID 41142443, 2025).
amyloid (7 papers, 2010 to 2022). "The more recent discovery of premature truncating mutations in PRNP linked to familial prion diseases has significantly expanded the phenotypic spectrum of PrP-amyloidosis." (PMID 35547619, 2022). "This inherited amyloidosis is caused by a number of mutations in the human gene, PRNP, on chromosome 20 that encodes the cellular prion protein (PrPC)." (PMID 29338055, 2018).
frontotemporal dementia (7 papers, 2019 to 2025). Frontotemporal dementia (FTD) comprises a group of neurodegenerative disorders, characterized by progressive changes in behavior, executive dysfunction and language impairment, as a result of degeneration of the medial prefrontal and frontoinsular cortices. "Notably, PRNP mutations have also been described in clinical pictures resembling other neurodegenerative diseases, such as frontotemporal dementia." (PMID 31340582, 2019).
Huntington disease (7 papers, 2014 to 2022). Huntington disease (HD) is a rare neurodegenerative disorder of the central nervous system characterized by unwanted choreatic movements, behavioral and psychiatric disturbances and dementia. "In addition to HTT, mutations in HDL3, JPH3 and PRNP genes were also related to Huntington's disease pathogenesis (OMIM database, retrieved on Dec." (PMID 27924190, 2016).
lung carcinoma (7 papers, 2019 to 2025). "Cellular prion protein (PrPc), encoded by PRNP gene, was previously found to enhance lung cancer invasiveness." (PMID 39972491, 2025). "This study is the first to uncover a novel regulatory pathway where c-Jun acts as a transcriptional repressor of miR-193b-3p, leading to PRNP upregulation, which promotes lung cancer migration and invasion." (PMID 39972491, 2025). "Together, these findings suggest that c-Jun, acting as a transcriptional repressor of miR-193b-3p, regulates PRNP expression and plays a key role in lung cancer metastasis." (PMID 39972491, 2025). "Taken together, our findings reveal that miR-193b-3p downregulates PrPc expression by directly targeting the 3'-UTR of PRNP, potentially contributing to lung cancer progression." (PMID 39972491, 2025). "Our study presents the first evidence of miR-193b-3p negatively regulating PRNP at the post-transcriptional level, thereby influencing tumor migration and invasion in lung cancer." (PMID 39972491, 2025). "Our research revealed that miR-193b-3p plays a crucial role as a regulator, suppressing PRNP expression and consequently inhibiting lung cancer cell proliferation, migration, and invasion." (PMID 39972491, 2025). "Intriguingly, the expression level of miR-193b-3p was higher in CL1-1 than in CL1-5, suggesting that miR-193b-3p may serve as a potential negative regulator of PRNP in lung cancer cells." (PMID 39972491, 2025). "Our findings provide evidence that PRNP is a direct target of miR-193b-3p in lung cancer." (PMID 39972491, 2025). "In this study, we explored the post-transcriptional regulation of PRNP in lung cancer cells." (PMID 39972491, 2025). "However, the specific involvement of miR-193b-3p in regulating PRNP expression, particularly in lung cancer, has not been fully explored." (PMID 39972491, 2025). "Regarding lung cancer, the PRNP gene is upregulated by NFIL3 in invasive lung adenocarcinoma (ILA) cell lines and, at the protein level, PrPC expression is widely observed in invasive tumors, but not in in situ tumors." (PMID 32932634, 2020).